BCR (BCR activator of RhoGEF and GTPase)
Diseases named in the same sentence as BCR in open-access papers (continued):
Sharing a sentence is not in itself a finding about the gene and the disease.
tumor (continued). "Future advances will require integrating time-series omics approaches with TCR/BCR sequencing, real-time imaging, and longitudinal sampling to capture the dynamic evolutionary trajectories of the tumor immune ecosystem with higher temporal resolution." (PMID 41562697, 2026). "This is likely due to the low initial infiltration of lymphoid cells and the rarity of EBV-transformed B-TILs with the BCR clonotype of interest themselves in the original tumor specimen." (PMID 41286066, 2025). "In our study, functional enrichment analysis of 2160 proteins commonly expressed in 13qCLL/MBL tumor cells identified critical phosphoproteins involved in BCR signaling, immune response regulation, and cell cycle regulation, such as BTK, PRKCB, STAT1, and SYK." (PMID 40129242, 2025). "On the other hand, in order to examine the impact of neddylation on non-BCR::ABL1-targeting anti-tumor drugs, two chemotherapeutic agents, cisplatin and doxorubicin, were used." (PMID 40447744, 2025). "This is consistent with the overall number of BCR clonotypes we observed in the original tumor tissue specimen (tum_burn0214)." (PMID 41286066, 2025). "Utilizing the scTCR/BCR-seq, we detected a greater number of clonotypes in T and B cells within mTLS, thus implying a higher probability for mTLS to recognize tumor neoantigens." (PMID 40335494, 2025). "These tumours also exhibited increased mutation rates, elevated neoantigen loads, and greater TCR/BCR diversity." (PMID 40159652, 2025). "Several lines of evidence suggest that CML is sensitive to immunotherapy, and that responses to TKI therapy can be determined not only by direct binding capacity for BCR::ABL but also by anti-tumor immune responses." (PMID 39136895, 2024). "From this input, CaClust aims to simultaneously reconstruct BCR hyperclusters of cells while assigning those hyperclusters to tumour clones." (PMID 39501370, 2024). "In summary, our analysis revealed the clonal and BCR hypercluster structure of the FL tumour samples, and allowed ranking them by the strength of genotypic explanation of transcriptional phenotypic heterogeneity." (PMID 39501370, 2024). "ZAP-70 induction in CLL B cells causes activation of specific BCR-signaling molecules, including SYK, BLNK, ERK, JNK, PLCγ, and AKT kinases, indicating ZAP-70 promotes the growth and survival of the tumor cells by stimulating BCR signaling." (PMID 38571491, 2024). "Together, these results suggest that higher absolute counts of Vδ1 and Vδ2 T cells found in patients with higher levels of tumor burden and BCR::ABL1 reflects the ongoing expansion of γδ T lymphocytes mediating antileukemic responses." (PMID 36376516, 2023). "According to PhosphoSitePlus29, CRKL pY207 is a known substrate of the tumor-driving fusion kinase BCR-ABL and can be regarded as a true responsive site of Dasatinib treatment." (PMID 38036588, 2023). "GSEA analysis indicated that CD22-mediated BCR modulation, cell cycle checkpoints, FCGR activation, and mitotic prometa centrally involve in regulating neoplasm development and immune response in high-risk individuals." (PMID 37059592, 2023). "The results manifested that the tumor size and BCR–ABL levels were significantly downregulated in the Arg-PEG1-Dasa–treated groups." (PMID 37392851, 2023). "Considering that ZFX silencing inhibited the growth of CML cells, our data indicated that ZFX facilitates leukemogenesis induced by BCR/ABL similar to its role in other tumor models induced by different oncoproteins, such as Hedgehog or MLL–AF9." (PMID 37864206, 2023).
tumor (continued). "For the analysis of immune repertoire in the baseline tumour samples, we found that BCR clonality (AUC=0.769) and BCR reads (AUC=0.744) at baseline also exhibited good predictive ability with regard to treatment efficiency." (PMID 36581917, 2022). "Bulk tumour gene expression analysis showed the BCR heavy chain isotype expression was, in order of abundance, IgG>IgA>IgM>IgD, measured in the TCGA SKCM RNA‐seq data; these samples spanned all stages of CM disease and outcomes." (PMID 35218154, 2022). "The molecular subtype of the primary tumor played a certain role in the engraftment velocity, with mice xenografted with patient samples harboring a BCR::ABL1 translocation demonstrating the lowest mean time to experiment termination." (PMID 35011712, 2022). "In vitro analysis revealed profound reduction of T cell proliferation, differentiation, cytokine release and killing of tumor cells upon application of BCR::ABL1 TKI with blinatumomab." (PMID 35551463, 2022). "We revealed the variable changes in clonal expansion of the TCR and BCR, laying the foundation for understanding of host anti-tumor immune mechanisms and immune reconstruction induced by chemotherapy." (PMID 36248860, 2022). "Switched memory B‐cells and increased BCR diversity are also significantly enriched in tumours from patients who responded to ICB, and some therapies enhance plasma cell TLS differentiation." (PMID 35218154, 2022). "It is commonly recognized that CLL is a BcR IG-dependent neoplasm, with antigen stimulation being a major protagonist in the pathogenesis of the disease." (PMID 35327406, 2022). "b‐AP15, an inhibitor of USP14 and UCHL5, exhibited potent tumour‐killing activity in BCR‐ABLWT and BCR‐ABLT315I CML cell lines, as well as in CML xenografts and primary CML cells." (PMID 36082692, 2022). "It has been previously reported that in some cancers the BCR light chain diversity of infiltrating B cells in the tumor region was significantly higher than the B cells in the nontumor region." (PMID 33463049, 2021). "For example, cancers harboring translocations that form fusion transcripts, such as BCR-ABL, or mutations, such as BRAF or EGFR, depend on these gene products’ activity for tumor maintenance." (PMID 34211974, 2021). "In a murine model, in which mice were injected with Ba/F3 cells via the tail vein, we found that TNK1-AAA-driven cells established rapid tumor burden and induced mortality with similar kinetics to BCR-ABL." (PMID 34504101, 2021). "BTK (Bruton’s tyrosine kinase) is critical for signal transduction downstream of the pre-B cell receptor (pre-BCR) and functions as a tumor suppressor in B-ALL42,43." (PMID 34764253, 2021). "Our data highlights the critical effect of treatment regimens for both drugs not only on the abrogation of BCR-dependent survival and proliferation signals but also on the activation of immune cells and establishing the functionality of non-tumour cells." (PMID 33431934, 2021). "To measure the ability of TNK1-driven Ba/F3 cells to grow in vivo, we stably integrated luciferase into the parental Ba/F3 cells for bioluminescent imaging of tumor burden, followed by retroviral expression of our panel of TNK1 variants and BCR-ABL." (PMID 34504101, 2021). "In this approach, we have combined low-dose chemotherapies that work to enhance tumor immunogenicity and antigen presentation aiding in BCR-recognition of TAAs." (PMID 34253827, 2021). "Several genes (including BCR, PCLO, ATXN3, PABPC3, and FADS6) were mutated in two or more PDX tumours." (PMID 33144587, 2020). "Among these were 6 members of the polycistronic miR-17-92 cluster, which are usually overexpressed and act as tumor promoters in a BCR/ABL- and c-myc-dependent manner in CML." (PMID 32927433, 2020). "Consistent with previous studies, we detected slightly higher TCR clonality and significantly higher BCR clonality in the responders, supporting the role of clonal expanded T and B cells in tumor elimination." (PMID 33059736, 2020).
tumor (continued). "PGE2 displays tumor suppressor functions in B-cells and other immune cells by impairing BCR activation and cell proliferation, as well as by triggering cell death." (PMID 31334126, 2019). "Similar to the lower number of TCR CDR3 calls in AML, the number of BCR CDR3 calls is also significantly lower in the AML samples compared to non-tumor samples." (PMID 31771646, 2019). "In transplants from TCL1 mouse D22 and 347, we observed a preserved major BCR clone, with expansion of one minor BCR clone from 0.5% in the primary tumor D22 to 21.3% in the 7th transplant." (PMID 30262843, 2019). "Genetic deletion of FOS inhibited tumor growth in a BCR‐ABL fusion protein kinase‐induced CML mouse model, and therefore, inhibition of high FOS expression reduced the intrinsic resistance of CML to TKI therapy." (PMID 31373443, 2019). "Efforts have been made to study the tumor-infiltrating TCR or BCR repertoires using either targeted deep sequencing (TCR-seq or BCR-seq) or unselected RNA-seq data in many solid tumors." (PMID 31771646, 2019). "Especially for targeted therapy regimen, testing for presence of drugable targets in or on tumor cells is mandatory (e.g., BCR/ABL1 or HER2)." (PMID 35582146, 2019). "For example, it was shown that tumor‐specific Hsp90 inhibitors disrupt BCR signaling at various steps, thus creating a situation where combination with BTK inhibitors yields synergistic killing of ABC‐DLBCL cells." (PMID 30874354, 2019). "In transplants descending from TCL1 mouse D22, we found the occurrence of additional mutations with increasing transplantation rounds, indicating significant clonal evolution within the original BCR clone during tumor growth in recipients." (PMID 30262843, 2019). "Similar to the lower TCR diversity, BCR CDR3 diversity in terms of CPK is also lower in AML samples than in non-tumor samples." (PMID 31771646, 2019). "We found that the formation of the Igβ/CD19 module is not only restricted to Ramos B cells but also expressed on other BL tumor lines and even on normal B cells with defective BCR expression." (PMID 29669863, 2018). "Shi X group demonstrated the apoptotic effect of gambogic acid on CML cells, mononuclear cells from imatinib mesylate -sensitive or -resistant patients and in xenograft tumor model bearing T315I-BCR-ABL genes or wild-type BCR-ABL." (PMID 29455667, 2018). "By phosphoproteomic analysis, we then identified BCR as an important DDR1 substrate involved in the maintenance of the β‐catenin oncogenic signalling necessary for tumour cell invasion." (PMID 29438985, 2018). "MM-released exosomes express the immunoglobulin B-cell receptor (Ig-BCR) of the tumor B-cells, which can be targeted by Idiotype-binding peptides (Id-peptides)." (PMID 29029605, 2017). "These anti-tumor effects are well correlated with the inhibition of BCR and JAK-STAT signaling and downstream inhibition of the functions of AKT, ERK and NF?B." (PMID 28088788, 2017). "As we have shown, SOCS1 can act as both a tumor suppressor and an oncogene in BCR-ABL mediated transformation." (PMID 28753604, 2017). "Ibrutinib exerts a potent anti-cancer effect by inhibiting BCR signaling and down-regulating NF-кB signaling, rapidly reducing tumor growth by inhibiting tumor proliferation and increasing apoptosis." (PMID 28716053, 2017). "The UHR is RNA isolated from 10 tumor cell lines, some which contain well characterized fusions (e.g. BCR-ABL fusion in the CML tumor cell line)." (PMID 27765019, 2016). "It was further suggested that miR-203 functions as a tumor-suppressor miRNA, targeting BCR-ABL and ABL kinases, which is epigenetically silenced in human Ph-positive leukemia cell lines." (PMID 26967056, 2016). "Losses in IgHV and IgKV clusters are presumably a sign of BCR rearrangement and cannot be considered as recurrent lesion in tumor samples." (PMID 27276707, 2016). "The BCR-ABL/STAT5/IRF-8 network is another example of the BCR-ABL ability to promote tumor suppressors inactivation." (PMID 27184141, 2016).
tumor (continued). "Future experiments using adoptively transferred BCR-transgenic B cells and appropriate tumor antigens need to be performed to shed light on this important aspect." (PMID 25821451, 2015). "For instance, inhibition of BCL-2 interacting mediator (BIM) expression by RNAi can inhibit the killing effect of imatinib on GISTs cells and BCR/ABL+ tumor cells." (PMID 24626299, 2014). "An enhanced anti-apoptotic capacity of tumor cells plays an important role in the process of breakpoint cluster region/Abelson tyrosine kinase gene (BCR/ABL)-independent imatinib resistance." (PMID 24626299, 2014). "In this study we used a conditional Stat3 knockout mouse model to investigate the consequences of Stat3 deletion for BCR/ABLp185+-driven tumor growth." (PMID 24473086, 2014). "For instance, IKAROS, encoded by IKZF1, has been shown to redirect BCR-ABL signaling from SFK activation to SLP65, which is downstream of the pre-B cell receptor tumor suppressor." (PMID 24130846, 2013). "Tumor DNA contained the germline configuration for BCR loci (IgH and IgK), but showed rearrangement of TCR loci (Jβ1 and Jβ2), confirming T-cell origin of disease." (PMID 24046360, 2013). "Many genes identified in our study are either known tumor suppressor genes (for example, BRCA1) or previously identified putative tumor suppressor genes (for example, BCR)." (PMID 21108794, 2010). "In neoplastic contexts, BCR signaling can become constitutively active or antigen‐independent, delivering continuous survival and proliferative signals that support tumor growth, facilitate immune evasion, and contribute to resistance to conventional chemotherapies." (PMID 40944468, 2025). "Furthermore, T cells in the tumour microenvironment modulate histone modifications, such as H3K9me3, which alter the efficiency of BCR signalling and contribute to therapeutic resistance." (PMID 40538372, 2025). "SIAIS056 effectively degraded various clinically significant resistance BCR-ABL (DC50 = 0.18 nM; for DAS-6–2-2–6-CRBN: DC50 = 30.5 nM) mutations and demonstrated strong tumour regression in K562 xenograft models (IC50 = 0.49 nM; for dasatinib: IC50 = 0.9 nM; for DAS-6–2-2–6-CRBN: 4.1 nM)." (PMID 40793752, 2025). "In addition to inducing apoptosis and reducing tumor cell viability, BCR pathway inhibitors also impair chemokine‐mediated migration and adhesion of tumor cells within protective lymphoid niches." (PMID 40944468, 2025). "Here, we use deep whole exome sequencing (WES), single cell RNA sequencing, single cell BCR sequencing (BCR-seq) and probabilistic modelling to deeply investigate the nature of tumour evolution as well as genotype to transcriptional phenotype interactions in four FL samples." (PMID 39501370, 2024). "Fourth, GSEA revealed the downregulation of genes for multiple pathways in plasma cells from tumours at the advanced stages, including BCR signalling, peptide biosynthetic process, and protein transport, which suggest decreased antibody production of plasma cells." (PMID 39231979, 2024). "For example, BCR and Ig sequencing may be leveraged to reveal whether TLS-associated plasma cell-derived IgG is relevant for tumor cell apoptosis and linked to clinical outcomes." (PMID 38629072, 2024). "Since, for these patients of our cohort, the real tumor load may be higher than that monitored by routine BCR::ABL1 assays (MR4.5), future follow-up may be informative." (PMID 37568730, 2023). "Imatinib prevents the proliferation of tumor cells that express BCR-ABL fusion proteins." (PMID 38239643, 2023). "A major characteristic of BCR::ABL1 is the induction of genomic instability associated with its leukemogenesis through the promotion of non-conservative DNA repair pathways and consequent increase in tumor mutation burden." (PMID 38067214, 2023).
tumor (continued). "Our finding that CLL clones retain the selection against replacement mutations in their IgHV FWRs indicates a need for IgH transcription, translation, and proper protein folding, and agrees with previous studies showing that CLL tumor clones depend on some type of signals from the BCR complex." (PMID 37007112, 2023). "Therefore, the higher the tumor load, as indicated by BCR::ABL1%, the longer an administered TKI therapy will take to reduce tumor cell burden to MMR levels (=0.1% BCR::ABL1 IS)." (PMID 37174118, 2023). "It is possible that Evi2a is a lymphocyte-specific tumor suppressor, which could play a role in BCR activation." (PMID 37244954, 2023). "In contrast, drugs with molecular targets: ABL, KIT, PDGF, SRC, and VEGFR were enriched in the drug clusters showing a strong effect on tumor cell intravasation with less impact on cell invasion or cell proliferation, of which, Imatinib, a multi-kinase inhibitor targeting BCR-ABL/PDGFR/KIT." (PMID 38239643, 2023). "In summary, through integrating cross-sectional analysis of single-cell RNA, TCR and BCR profiles from paired ascites, tumor and peripheral blood samples, we provided important insight into the TME in an HGSOC patient with several cycles of relapse and chemo-resistance." (PMID 36248860, 2022). "Moreover, oral administration of pterostilbene significantly suppressed tumor growth in mice transplanted with BCR/ABL+ leukemic cells." (PMID 35027628, 2022). "B‐cell epitope spreading likely occurs simultaneously with their role as antigen‐presenting cells, where their BCR binds antigen from lysed tumour, processes and presents novel epitopes cells to T‐cells, which in turn become activated by TH‐cells of linked specificity." (PMID 35218154, 2022). "Besides the heterogeneity and TCR/BCR clonal evolution of stromal and immune cells, tumor histological regions are demarcated by TME to form heterogeneous tumor organization." (PMID 35514975, 2022). "H&E staining also revealed significantly fewer tumour cells in BCR/ABL-targeted tumours." (PMID 35742831, 2022). "Specifically, these mutations are located on five tumor suppressors (SDHA, RB1CC1, PTCH1, DMBT1, BCR) and eight proto-oncogenes (MERTK, CSF1R, MYB, ROS1, PCM1, FGFR2, MYH11, BRCC3) and have an allele frequency lower than 0.01 in the Genome Aggregation Database (GnomAD)." (PMID 33466296, 2021). "In typical CLL cases, the tumor B cell clone exhibits an abnormal expression of markers like CD5, CXCR4, and ZAP-70, that are used to stratify the disease in conjunction with the mutational status of the BCR reflecting different cell of origin." (PMID 34956214, 2021). "We next asked whether there were specific types of BCR genes expressed only in the tumor tissue of CRC." (PMID 33463049, 2021). "In B-lymphoproliferative disorders, the BcR plays a key role in the development, proliferation, and survival of tumor B cells, by an antigen-driven process that triggers a molecular cascade of events that lead to transcriptional activation of proinflammatory, proliferative and antiapoptotic genes." (PMID 33466993, 2021). "As an example, we demonstrated that the introduction of n-glycosylation acceptor sites harboring unusual high-mannose oligosaccharides in FL BCR triggers the interaction of malignant B cells with DC-SIGN-expressing tumor-infiltrating macrophages resulting in BCR-dependent FL B cell activation." (PMID 33028033, 2020). "This method has been applied to study cells from the primary tumor and tumor-associated lymph node of a breast cancer patient and demonstrated the ability to track clonally related lymphocytes across tissues and link TCR and BCR clonotypes with gene expression features." (PMID 32793500, 2020).